YTHDF2 (YTH N6-methyladenosine RNA binding protein F2)
Description:
Specifically recognizes and binds N6-methyladenosine (m6A)- containing RNAs, and regulates their stability. M6A is a modification present at internal sites of mRNAs and some non-coding RNAs and plays a role in mRNA stability and processing. Acts as a regulator of mRNA stability by promoting degradation of m6A-containing mRNAs via interaction with the CCR4-NOT and ribonuclease P/MRP complexes, depending on the context. The YTHDF paralogs (YTHDF1, YTHDF2 and YTHDF3) share m6A-containing mRNAs targets and act redundantly to mediate mRNA degradation and cellular differentiation. M6A-containing mRNAs containing a binding site for RIDA/HRSP12 (5'-GGUUC-3') are preferentially degraded by endoribonucleolytic cleavage: cooperative binding of RIDA/HRSP12 and YTHDF2 to transcripts leads to recruitment of the ribonuclease P/MRP complex. Other m6A-containing mRNAs undergo deadenylation via direct interaction between YTHDF2 and CNOT1, leading to recruitment of the CCR4-NOT and subsequent deadenylation of m6A-containing mRNAs. Required maternally to regulate oocyte maturation: probably acts by binding to m6A-containing mRNAs, thereby regulating maternal transcript dosage during oocyte maturation, which is essential for the competence of oocytes to sustain early zygotic development (By similarity). Also required during spermatogenesis: regulates spermagonial adhesion by promoting degradation of m6A-containing transcripts coding for matrix metallopeptidases (By similarity). Also involved in hematopoietic stem cells specification by binding to m6A-containing mRNAs, leading to promote their degradation. Also acts as a regulator of neural development by promoting m6A-dependent degradation of neural development-related mRNA targets (By similarity). Inhibits neural specification of induced pluripotent stem cells by binding to methylated neural-specific mRNAs and promoting their degradation, thereby restraining neural differentiation. Regulates circadian regulation of hepatic lipid metabolism: acts by promoting m6A-dependent degradation of PPARA transcripts. Regulates the innate immune response to infection by inhibiting the type I interferon response: acts by binding to m6A-containing IFNB transcripts and promoting their degradation. May also act as a promoter of cap-independent mRNA translation following heat shock stress: upon stress, relocalizes to the nucleus and specifically binds mRNAs with some m6A methylation mark at their 5'-UTR, protecting demethylation of mRNAs by FTO, thereby promoting cap-independent mRNA translation. Regulates mitotic entry by promoting the phase-specific m6A-dependent degradation of WEE1 transcripts. Promotes formation of phase-separated membraneless compartments, such as P-bodies or stress granules, by undergoing liquid-liquid phase separation upon binding to mRNAs containing multiple m6A-modified residues: polymethylated mRNAs act as a multivalent scaffold for the binding of YTHDF proteins, juxtaposing their disordered regions and thereby leading to phase separation. The resulting mRNA-YTHDF complexes then partition into different endogenous phase-separated membraneless compartments, such as P-bodies, stress granules or neuronal RNA granules. May also recognize and bind RNAs modified by C5-methylcytosine (m5C) and act as a regulator of rRNA processing. (Microbial infection) Promotes viral gene expression and replication of polyomavirus SV40: acts by binding to N6-methyladenosine (m6A)-containing viral RNAs. (Microbial infection) Promotes viral gene expression and virion production of kaposis sarcoma-associated herpesvirus (KSHV) at some stage of the KSHV life cycle (in iSLK.219 and iSLK.BAC16 cells). Acts by binding to N6-methyladenosine (m6A)- containing viral RNAs.
Synonyms: DF2; HGRG8; NY-REN-2; CAHL
Tractability: Small molecule: a structure with a bound ligand is known; a high-quality ligand is known. PROTAC: UniProt records ubiquitination sites on it; ubiquitination databases record sites on it; its protein half-life has been measured.
Gene: Protein-coding gene on chromosome 1 (28,736,621 to 28,769,784, forward strand). Ensembl gene ENSG00000198492.
Subcellular location: Cytoplasm, cytosol; Cytoplasm, P-body; Cytoplasm, Stress granule; Nucleus
Subcellular location (Human Protein Atlas): Cytosol; Cytoplasmic bodies
Gene Ontology:
Molecular function: C5-methylcytidine-containing RNA reader activity; N6-methyladenosine-containing RNA reader activity; protein binding; RNA binding
Biological process: mRNA catabolic process; mRNA destabilization; negative regulation of stem cell differentiation; negative regulation of type I interferon-mediated signaling pathway; organelle assembly; positive regulation of cap-independent translational initiation; positive regulation of translational initiation; regulation of mRNA stability; regulation of neurogenesis; regulation of rRNA processing; stress granule assembly; embryonic morphogenesis; endothelial to hematopoietic transition; gamete generation; hematopoietic stem cell proliferation; humoral immune response; negative regulation of Notch signaling pathway; oocyte maturation; regulation of cell adhesion; regulation of hematopoietic stem cell differentiation; regulation of meiotic cell cycle process involved in oocyte maturation; spermatogonial cell division
Cellular component: cytoplasm; cytoplasmic ribonucleoprotein granule; cytoplasmic stress granule; cytosol; nucleus; P-body
Genetic constraint (gnomAD): Loss-of-function variants: 2 observed, 47.67 expected, observed/expected ratio (o/e) 0.042, 90% interval 0.016 to 0.13. The upper end of that interval is the gene's LOEUF score, 0.13, which puts it in group 1 of 6, group 1 being the genes least tolerant of losing a copy. Missense variants: 476 observed, 726.67 expected, observed/expected ratio (o/e) 0.66, 90% interval 0.61 to 0.71. Synonymous variants: 216 observed, 259.49 expected, observed/expected ratio (o/e) 0.83, 90% interval 0.74 to 0.93.
Homologues: Orthologues: mouse Ythdf2 (99% identical), rabbit YTHDF2 (99% identical), macaque YTHDF2 (99% identical), dog YTHDF2 (99% identical), pig YTHDF2 (98% identical), chimpanzee YTHDF2 (98% identical), rat Ythdf2 (94% identical), guinea pig YTHDF2 (91% identical), zebrafish ythdf2 (77% identical), tropical clawed frog ythdf2 (66% identical), Drosophila melanogaster Ythdf (35% identical). Paralogues in human: YTHDF3 (68% identical), YTHDF1 (65% identical), YTHDC1 (18% identical).
Diseases named in the same sentence as YTHDF2 in open-access papers:
YTHDF2 is named in the same sentence as 205 diseases in open-access papers, as found by Europe PMC text mining. Sharing a sentence is not in itself a finding about the gene and the disease. The quoted sentences say what the papers report.
hepatocellular carcinoma (114 papers, 2018 to 2025). A malignant tumor that arises from hepatocytes. "YTHDF2 expression is inversely associated with overall survival in hepatocellular carcinoma patients, indicating a poor prognostic signature, and the knockdown of YTHDF2 leads to impaired stemness." (PMID 40986143, 2025). "YTHDF2 is an m6A reader, which has been proved to be associated with the prognosis of patients with hepatocellular carcinoma." (PMID 35530319, 2022). "YTHDF2 silencing in human hepatoma cells or ablating in mouse hepatocytes can cause inflammation, vascular reconstruction, or cancer metastasis." (PMID 33552994, 2020). "In hepatocellular carcinoma (HCC), YTHDF2 facilitates the m6A-dependent translation of ETS variant transcription factor 5 (ETV5), which induces PD-L1 transcription and suppresses CD8 + T-cell-mediated antitumor immunity." (PMID 39987091, 2025). "In hepatocellular carcinoma, an inverse relationship was observed between YTHDF2 expression and patient survival rates." (PMID 41369154, 2025). "Studies coupling YTHDF2 with METTL14 unveil that YTHDF2-mediated degradation of SLC7A11 mRNA necessitates METTL14-mediated RNA m6A modification in hepatocellular carcinoma." (PMID 40327848, 2025). "In a study of hepatocellular carcinoma, silenced YTHDF2 was found to provoke inflammation, vascular reconstruction, and metastatic progression." (PMID 38693353, 2024). "In hepatocellular carcinoma, YTHDF2 modulates m6A methylation for OCT4 mRNAs, promoting cancer metastasis and cancer stem cell liver phenotype." (PMID 39075530, 2024). "For instance, METTL3 is associated with poor prognosis in hepatocellular carcinoma (HCC) patients and promotes HCC cell proliferation through YTHDF2-mediated silencing of SOCS2 transcription." (PMID 38970366, 2024). "Conversely, other studies have shown that YTHDF2 inhibits cell proliferation and growth in hepatocellular carcinoma by destabilizing EGFR mRNA." (PMID 38397033, 2024). "Several studies have suggested that YTHDF2 can act as a tumor suppressor in hepatocellular carcinoma (HCC)." (PMID 39342406, 2024). "Silencing of m6A reader YTHDF2 can provoke inflammation, vascular reconstruction, and metastatic progression in hepatocellular carcinoma." (PMID 37355654, 2023). "It has been reported that overexpressed YTHDF2 promotes carcinogenesis; yet, its role in hepatocellular carcinoma (HCC) is elusive." (PMID 37515378, 2023). "CCK-8 and colony formation assays indicated that depletion of YTHDF2 markedly inhibited cell proliferation in HBV-infected hepatoma cells, which was rescued by re-expression of YTHDF2-WT but not YTHDF2-S263A." (PMID 36765030, 2023). "In hepatocellular carcinoma, some scholars postulate that YTHDF2 promotes cancer development; however, others scholars observed that YTHDF2 suppresses cell proliferation and growth." (PMID 35186724, 2022). "YTHDF2 is known to inhibit hepatocellular carcinoma cell proliferation and growth by inhibiting EGFR mRNA stability." (PMID 36479088, 2022). "In hepatocellular carcinoma, YTHDF2 has been reported to affect tumor angiogenesis and inhibit tumor progression." (PMID 35982895, 2022). "A novel study on hepatocellular carcinoma found that YTHDF2 facilitated the degradation of circCPSF6 containing m6A modification." (PMID 35840930, 2022). "Further, YTHDF2 was dysregulated and played an oncogenic role in bladder cancer, hepatocellular carcinoma, cervical cancer, gastric cancer and pancreatic cancer." (PMID 35696608, 2022). "In hepatocellular carcinoma, YTHDF2 directly binds to the m6A modification site of the 3′‐UTR of EGFR to promote the degradation of EGFR mRNA." (PMID 34647424, 2022). "Among these prognosis-related m6A regulators, a number of previous studies have indicated that YTHDF2 is primarily involved in the malignant progression of pancreatic cancer, hepatocellular carcinoma, and acute myeloid leukemia." (PMID 35559023, 2022).
hepatocellular carcinoma (continued). "YTHDF2 inhibition promotes cell growth by reducing the m6A modification-induced degradation of EGFR mRNA in hepatocellular carcinoma (HCC) cells." (PMID 35669241, 2022). "Some studies suggest that YTHDF2 can promote the stemness phenotype of hepatoma cells by regulating the m6A methylation of the Oct4 gene." (PMID 35530319, 2022). "Other studies have shown that YTHDF2 can be regarded as a tumor suppressor, inhibiting the growth of hepatoma cells." (PMID 33692959, 2021). "YTHDF1 plays a crucial part in the regulation of cell cycle and metabolism of hepatocellular carcinoma, while YTHDF2 exerts an inhibitory effect on hepatocellular carcinoma cells." (PMID 34794452, 2021). "In a study of m6A methylation in hepatocellular carcinoma, hypoxic states were concomitant with reduced YTHDF2 levels, and this effect was predominantly exerted by HIF2α repression rather than HIF1α." (PMID 33616673, 2021). "YTHDF2 is negatively regulated by miR-145/miR-495/miR-493-3p at post-transcriptional level in hepatocellular carcinoma cells and prostate cancer cells." (PMID 34872591, 2021). "For example, the high expression of YTHDF1 and YTHDF2 was related to the poor prognosis of patients with hepatocellular carcinoma, indicating that it promotes proliferation and inhibits invasion and metastasis." (PMID 33779693, 2021). "Also in hepatocellular carcinoma (HCC), the inhibition of miR-145 causes an increase in YTHDF2 expression which in turn leads to a fall in the levels of m6A, probably due to increased mRNA degradation." (PMID 33461542, 2021). "For example, YTHDF2 is highly expressed in hepatocellular carcinoma and specifically reads the m6A modification of OCT4, and enhances its expression, which promotes the liver cancer stem cell phenotype and cancer metastasis." (PMID 34347395, 2021). "In hepatocellular carcinoma (HCC), YTHDF2 was found to be reversely associated with the survival of patients." (PMID 34539889, 2021). "A previous study showed that YTHDF2 expression was regulated by miR-145 in hepatocellular carcinoma (HCC) cells." (PMID 32986017, 2020). "Previous studies have demonstrated that YTHDF1 and YTHDF2 are highly expressed in hepatocellular carcinoma, affecting cell cycle and metabolism of tumor cells, and the prognosis of high YTHDF1 expression in patients was poor." (PMID 32631107, 2020). "Here, 13 differentially expressed m6A methylation regulators were confirmed in 374 hepatocellular carcinoma (HCC) patients, among which RBM15, YTHDC1, YTHDF1, and YTHDF2 were significantly variant in different stages and grades." (PMID 32974160, 2020). "In hepatocellular carcinoma, YTHDF2 not only exhibits a cancer-promoting effect, but also can exert a cancer-suppressing effect." (PMID 33552994, 2020). "The observation of similar effects after manipulating METTL3 and YTHDF2 expression supports the concept that the axis consisting of m6A writer and m6A reader is likely to exist in BCa, analogous to a previous study in hepatocellular carcinoma." (PMID 32126149, 2020). "Taken together, the regulation of YTHDF2 by miR-145 plays an important role in the biological function of hepatoma cells." (PMID 31757221, 2019). "YTHDF2, an m6A reader, has been implicated in the regulation of hepatocellular carcinoma (HCC)." (PMID 29423080, 2018). "In studies on hepatocellular carcinoma, YTHDF2 acts in an m6A-dependent Manner on its downstream direct target ETS variant transcription factor 5 (ETV5), regulating ETV5 mRNA translation to negatively modulate its protein levels and thereby influence VEGFA production." (PMID 40986143, 2025). "A recent study also highlighted the important role of YTHDF2 in hepatocellular carcinoma (HCC)." (PMID 40271153, 2025). "O-GlcNAcylation could inhibit the YTHDF2 ubiquitination and increase its protein stability, which promotes the progression of HBV-associated hepatocellular carcinoma." (PMID 41369154, 2025).
hepatocellular carcinoma (continued). "However, YTHDF2 functions as a revisable role in hepatocellular carcinoma to disrupt ERGF mRNA stability." (PMID 37256443, 2024). "Furthermore, transwell and wound-healing assays also showed that YTHDF2 knockdown decreased the invasion and migration abilities of hepatoma cells." (PMID 36765030, 2023). "Hypoxia-induced YTH-domain family 2 (YTHDF2) is reported to inhibit hepatocellular carcinoma (HCC) growth via destabilizing EGFR mRNA, which may contribute to resistance to tumorigenesis in a hypoxic environment." (PMID 35794625, 2022). "In addition, YTHDF2 inhibits the normalization of tumor vasculature in hepatocellular carcinoma cells by increasing the attenuation of IL11 and SERPINE2 mRNAs." (PMID 35572524, 2022). "Moreover, studies showed that overexpression of YTHDF2 suppresses tumor growth in hepatocellular carcinoma." (PMID 35937999, 2022). "HIF-2α is reported to transrepress YTHDF2 in hepatocellular carcinoma cells." (PMID 34872591, 2021). "Moreover, the knockdown of YTHDF2 in hepatoma cells inhibited the release of inflammatory cytokines and reduced macrophage clearance of hepatoma cells." (PMID 34881240, 2021). "Besides, a previous study indicated that miR-145 modulates the m6A levels in clinical hepatocellular carcinoma (HCC) tissues by targeting the 3’UTR of YTHDF2 mRNA." (PMID 33853538, 2021). "For example, hsa-miR-145 could regulate the expression of YTHDF2 in hepatocellular carcinoma, which further affected the m6A modification and promoted the disease progression." (PMID 33718187, 2021). "METTL3 was shown to promote the proliferation and migration of hepatocellular carcinoma via the YTHDF2-dependent pathway and its knockdown could inhibit tumor progression." (PMID 33240891, 2020). "The expression of YTHDF2 is up‐regulated in hepatocellular carcinoma, pancreatic cancer, etc, the expression of YTHDF1 is up‐regulated in colorectal cancer, hepatocellular carcinoma, ovarian cancer, lung cancer, etc, and both YTHDF1 and YTHDF2 are independent risk factors for OS." (PMID 32808488, 2020). "Similarly, YTHDF2 was shown to be involved in the progression and angiogenesis in hepatocellular carcinoma, and its inhibition exhibited promising efficacy in acute myeloid leukemia." (PMID 33240891, 2020). "Studies have shown that the overexpression of YTHDF2 in hepatocellular carcinoma (HCC) can inhibit tumor cell growth, whereas the knockout of the YTHDF2 gene promotes angiogenic sprouting in human umbilical vein endothelial cells (HUVECs)." (PMID 39295872, 2024). "Therefore, a reduction in hypoxia-sensitive YTHDF2 could reprogram the m6 A-edited transcriptome and promote the development of hepatocellular carcinoma (HCC)." (PMID 38053093, 2023). "In hepatocellular carcinoma, YTHDF2 silenced in human HCC cells or ablated in mouse hepatocytes provoked inflammation, vascular reconstruction, and metastatic progression." (PMID 35309512, 2022). "In hepatocellular carcinoma (HCC), one research shows that YTHDF2 expression has a positive correlation with HCC progression whereas another research reports that YTHDF2 suppressed HCC tumor growth through accelerating EGFR mRNA degradation." (PMID 36008805, 2022). "The expression of YTHDF2 in Hepatocellular Carcinoma (HCC) increases, which is closely related to the malignant degree of HCC." (PMID 33692959, 2021). "In hepatocellular carcinoma (HCC), YTHDF2 was downregulated in response to hypoxia leading to HCC cell proliferation." (PMID 33814008, 2021). "Among the many different kinds of tumors, hepatocellular carcinoma (HCC) is one in which YTHDF2 has been studied the most." (PMID 33795663, 2021). "The overexpression of YTHDF2 in hepatocellular carcinoma (HCC) promoted stemness and metastasis via increasing OCT4 translation." (PMID 34804925, 2021). "In hepatocellular carcinoma, m6A methylation of vascular endothelial growth factor A (VEGFA) mRNA was modified by methyltransferase RBM15 and two readers, YTHDF2 and IGF2BP3." (PMID 41272900, 2025).